STAT3 (signal transducer and activator of transcription 3)
Diseases named in the same sentence as STAT3 in open-access papers (continued):
Sharing a sentence is not in itself a finding about the gene and the disease.
cancer (continued). "The signal transducer and activator of transcription 3 (STAT3) and YY1-associated protein 1 (YY1AP1) are two oncogene factors in cancer cells." (PMID 32380783, 2020). "Meanwhile, all of these effects were abrogated either by adding IL6 neutralizing antibodies to the co‐cultured CM or by downregulating STAT3 or gp130 expression in cancer cells." (PMID 32308766, 2020). "Increased IL6 expression has been reported to activate STAT3 signaling, subsequently involving drug resistance and cancer progression." (PMID 32963220, 2020). "It has been demonstrated that aberrant STAT3 activation in cancer plays a key role in invasion and metastasis." (PMID 32328465, 2020). "STAT3 is constitutively active in a variety of human malignancies and regulates the expression of target genes involved in tumorigenesis and cancer progression." (PMID 32495998, 2020). "The activation of S1PR1/STAT3 amplification loop seems to be an inherent feature of other cancer types as well and targeting this signaling axis using S1PR1 antagonist FTY720 has already yielded promising results." (PMID 32456134, 2020). "Cucurbitacin B results in G2/M phase arrest and the induction of the caspase cascade as a result of STAT3 inhibition in cancer cells." (PMID 32731620, 2020). "Our previous study showed that YM155 not only decreased DNA damage repair, but also decreased radiation-induced invasion and reversed EMT by inhibiting STAT3, which was a promising radiosensitizer in the treatment of cancer." (PMID 32733808, 2020). "The results from several studies indicate that STAT3 functions as an integration center for various cancer cell signals through its nuclear and mitochondrial activities." (PMID 33003453, 2020). "As such, dysregulated STAT3 activation is positively correlated with a majority of cancers; regulating functional pleiotropic responses ranging from cell proliferation to angiogenesis to metastasis." (PMID 32331320, 2020). "In particular, IL‐6 is well known as a critical regulator of STAT3 activation in most kinds of cancers." (PMID 32491253, 2020). "Napabucasin (BBI608) is an orally bioavailable small molecule known to inhibit cancer stem cells’ activity in the JAK2/STAT3 pathway." (PMID 33158194, 2020). "RKIP inhibits the metastatic potential of cancer through the reduction of IL-6, Raf, or c-Src-mediated STAT3 activation by direct interaction with STAT3." (PMID 31952344, 2020). "Our findings reveal FBP1 as an upstream inhibitor of STAT3 and uncover a new mechanism that regulates the function of STAT3 in cancer." (PMID 31938049, 2020). "Among them, IL6 is a well-characterized cytokine that has been reported to be involved in various cancers progression by stimulating JAK2/STAT3 pathway." (PMID 32963220, 2020). "Collectively, these data suggested that FOXD2-AS1 is a regulator of STAT3 that functions to control the maintenance of cancer stemness and chemotherapy resistance in LSCC." (PMID 31959918, 2020). "Among these molecules, S3I-201, STA-21, C188, and STX-0119 were shown to block the phosphorylation, dimerization, DNA binding, and transcriptional activity of STAT3 as well as growth and survival of cancer cells." (PMID 31963765, 2020). "Alternatively, treatment of lung adenocarcinoma with cisplatin enhances IL-11 secretion by CAFs, which in turn promotes resistance of cancer cells to CT through the STAT-3 signaling pathway." (PMID 33553157, 2020). "Reciprocally, educated SCs secret IL6 to activate STAT3 signaling in cancer cells, thus augmenting cancer cell invasion and metastasis in vitro and in vivo." (PMID 32308766, 2020). "The gain-of-function mutations in STAT3 and STAT5b genes up to now remain the most frequent abnormalities in LGLL, even if additional genetic lesions in STAT-related or cancer genes have been described." (PMID 32133291, 2020). "STAT3 expression has been reported to correlate with poor patient outcome in several types of cancer." (PMID 32552789, 2020).
cancer (continued). "Inhibition of the IL-6/STAT3 pathway is a promising approach for cancer treatment; however, STAT3 inhibitors that can be used at present in clinical cancer therapy are limited in their efficiency, specificity, and safety." (PMID 31511651, 2020). "STAT3 has been found to be persistently activated in many types of cancers, primarily through its tyrosine phosphorylation (Y705)." (PMID 32231398, 2020). "Napabucasin is a cancer stemness inhibitor that targets a number of oncogenic pathways, including signal transducer and activator of transcription 3 (STAT3)." (PMID 32236642, 2020). "STAT3 is constitutively activated in numerous types of human cancers, including ECSS, and plays a key role in regulating proliferation, chemo-resistance, and relapse." (PMID 33390934, 2020). "Phosphorylation of STAT3 stimulates different cancer related proteins, such as Bcl-xl, Bcl-2 (tumorigenesis), Cyclin D1 (proliferation), MMP-9 (invasion), and VEGF (angiogenesis)." (PMID 33260759, 2020). "In a positive feedback loop, PKM2 localizes to the nucleus in rapidly growing cancer cells, where it phosphorylates STAT3 to increase its transcriptional activity." (PMID 33003453, 2020). "By the inhibition of STAT3, the induction of angiogenesis is inhibited and the growth of cancer cells is inhibited." (PMID 32545648, 2020). "EGCG inhibits VEGF production through decreasing both the constitutive activation of Stat3 and NF-kappa B, in cancer cells." (PMID 32660101, 2020). "Overall, the data revealed that betulinic acid regulated STAT3 in cancer, suggesting the potential role of betulinic acid as a chemopreventive compound targeting STAT3." (PMID 32486001, 2020). "Studies have shown that the STAT3 pathway is involved in IL-6 regulation of several cancer cell functions, such as proliferation and metastasis." (PMID 32201532, 2020). "Several cancer-preventive and naturally occurring agents have been reported to target STAT3 molecule." (PMID 32224910, 2020). "Despite its sustaining role in cancer progression, drug resistance and metastasization, STAT3 can also act as a protective factor in normal cells, wherein it controls different genes, such as those involved in proliferation, survival and self-renewal." (PMID 32252311, 2020). "In respect to the role of STAT3 in the development and progression of cancer, a variety of clinical trials have focused on targeting STAT3 in the treatment of patients with cancer." (PMID 32545648, 2020). "PTPRT, another negative regulator of the JAK/STAT pathway, is silenced via promoter hypermethylation in many cases of HNC and provides a likely mechanism for STAT3 hyperactivation in this cancer." (PMID 33521321, 2020). "One way to prevent STAT-3 activation is to inhibit thetyrosine kinase events at receptor level, which is unfeasible in most cancers.." (PMID 32167126, 2020). "Accumulated evidences suggest that aberrant Stat3 signaling is required for the initiation, development and progression of several human cancers, including OS." (PMID 32549792, 2020). "In cancer, STAT3 supports oncogenesis, cell death resistance, anti-tumor immunity evasion, therapy resistance and additional critical processes for cancer development [2,]." (PMID 32863208, 2020). "Given the key role of STAT3 in GSC propagation and the importance in targeting this population for effective anti-cancer therapies, here our primary objective was to address the functional characterization of Gint4.T-STAT3 on GSCs." (PMID 32486489, 2020). "In cancers, STAT3 is persistently activated due to the disruption of a negative regulatory system, which results in the overexpression of oncogenic proteins." (PMID 32967366, 2020).
cancer (continued). "The most prevalent mechanism of STAT3 activation in cancer is via the pro-inflammatory cytokine IL-6." (PMID 32899142, 2020). "Studies have shown that chronic inflammation mediated by the transcription factors STAT3 and NF-κB in HTLV-1, EBV and KSHV-infected cells play critical roles in the development of viral-associated cancers." (PMID 33182552, 2020). "As a consequence, downstream targets of STAT3 including, c-Myc, Survivin and Bcl-xl, undergo upregulation that ensures the viability and proliferation of cancer cells." (PMID 32545648, 2020). "It is reported that STAT3 contributes to muscle wasting in PDX animal models, as constitutively active STAT3 induces muscle fiber atrophy and exacerbates wasting in cancer cachexia in an NF-kB dependent manner." (PMID 31941005, 2020). "FCs modulate several pathways inducing cancer cell death by inhibiting signal transducer and activator of transcription 3 (STAT3), nuclear factor-κB (NF-κB), phosphatidylinositol-3-kinase and AKT protein expression." (PMID 32911753, 2020). "In the cancer cells which rely on STAT3-mediated increase of NNMT expression, this can be of the utmost importance." (PMID 33182817, 2020). "Constitutively-activated STAT3 has been frequently detected in human cancers and contributes to cancer progression." (PMID 32872659, 2020). "Modulation of molecular pathways by EGCG also affects transcription factors such as Signal Transducer and Activator of Transcription 3 (STAT3) and Activating Protein-1 (AP-1) implicated in pathogenesis of cancer." (PMID 33167519, 2020). "Particularly, the development of inhibitors blocking STAT3 transcriptional activity appears to be a promising therapeutic approach against cancer." (PMID 33299414, 2020). "Twist is a transcription factor that directly regulated by STAT3, and STAT3-mediated TWIST gene expression is responsible for cancer cell EMT." (PMID 32536866, 2020). "This is consistent with several reports showing that NEAT1 promotes cancer progression by enhancing STAT3 signaling." (PMID 32843056, 2020). "At the moment, although it is known that complex and not entirely understood mechanisms regulate STAT3 signaling in normal and cancerous cells, inhibiting STAT3 activation seems to represent an interesting novel strategy for cancer treatment." (PMID 33081075, 2020). "Activation of miR-21 expression via STAT3 represents an epigenetic switch linking inflammation to cancer." (PMID 32751207, 2020). "The efficacy of inhibiting STAT3 increases under nutrient challenging conditions, suggesting that cancer cells experiencing metabolic stress rely on STAT3 for their survival." (PMID 32731620, 2020). "In this regard, it should be noted that PDIA3 modulates STAT3 signaling and that PDIA3 up- or downregulation has been related to cancer progression and inhibition of proliferation, respectively, through STAT3." (PMID 33153019, 2020). "Compound 23 showed high potency in inducing cancer cell apoptosis and ROS generation, inhibiting STAT3 phosphorylation on Tyr705, affecting mitochondrial membrane potential and preventing STAT3 DNA-binding activity." (PMID 32610556, 2020). "The importance of the IL-6R/JAK/STAT3 signalling pathway for tumourigenesis is evident, as it is estimated to be aberrantly activated in >70% of human cancers." (PMID 32731620, 2020). "Overall, EVO can attenuate the activation of c-Met/Src/STAT3 pathways and act as a modulator of cancer cell survival, proliferation, and angiogenesis." (PMID 32183146, 2020). "STAT3 is activated in a variety of tumors and is thought to be required for the maintenance of cancer stem cells." (PMID 33374980, 2020). "To demonstrate the underlying molecular mechanism of HHDMNQ-induced ROS-mediated apoptosis of A549 cells, we examined the effects of HHDMNQ on MAPK, STAT3, and NF-κB signalling pathways that play pivotal roles in cancer cells." (PMID 32849902, 2020).
cancer (continued). "Although the role of STAT3 in tumorigenesis needs to be elucidated, it is clear that STAT3 is an advantageous drug target for cancer treatment." (PMID 32486001, 2020). "Our previous study showed that Trichomicin, a natural compound derived from Trichoderma hazianum, exerted potent anti-inflammatory and anticancer activity in vitro, and induced apoptosis in cancer cells through inhibition of IL-6/Stat3 signaling." (PMID 32317968, 2020). "Then, we summarized the top 10 compounds whose drug response were significantly related to STAT3 expression in 10 cancer cell line types separately." (PMID 32486001, 2020). "BBI-608 is a small-molecule STAT3 inhibitor that can directly inhibit STAT3-driven signaling activation, a critical regulator of cancer stemness." (PMID 33312953, 2020). "In a panel of 15 cancer cell lines, S222 and S439 inhibited STAT3 phosphorylation, induced DNA double-strand breaks, blocked cell cycle at G2/M phase, and induced apoptosis." (PMID 32265690, 2020). "A high amount of fibroblasts was also associated with a higher infiltration of anti-cancer immune cells, such as CD8+ T-cells and dendritic cells, together with higher inflammatory signaling, including IL2/STAT5 and IL6/JAK/STAT3 signaling." (PMID 32485981, 2020). "One of the major factors that drives MDSC expansion in cancer is transcriptional factor signal transducer and activator of transcription 3 (STAT3)." (PMID 32005273, 2020). "In cancer cells, aberrant IL-6 signaling and constitutive activation of Stat3 are closely related to cell proliferation and drug resistance." (PMID 32211606, 2020). "Actually, various studies showed STAT-3 as a promising cancer drugtarget, so a rationale can be developed for the discovery and design ofanti-cancerous drugs." (PMID 32167126, 2020). "Increasing evidence demonstrates that tumorigenesis and EMT can be regulated by transcription factor STAT3 in cancer cells." (PMID 32784711, 2020). "Below, we summarize currently existing evidence of functional and direct collaborations between CD44 and STAT3 signaling pathways across various cancer models." (PMID 33335857, 2020). "In this study, we demonstrated that STAT3 expression was closely correlated with immune infiltration in cancer." (PMID 32486001, 2020). "JAK2/STAT3 pathway plays an important role in cell proliferation, differentiation and inhibition of apoptosis in number of cancers." (PMID 33123268, 2020). "Western blotting assays showed that the addition of co-cultured CM to cancer cells led to dramatic STAT3 activation." (PMID 32308766, 2020). "STAT3 blockade can also markedly improve other effective immunotherapeutic approaches including cancer vaccines and immunostimulatory Toll-like receptor (TLR) agonists (such as CpG oligodeoxynucleotides)." (PMID 32972405, 2020). "Several genes and pathways that are relevant in cancer initiation and progression have been identified in our study as dysregulated by the miR-124/STAT3 axis in CTCL." (PMID 33333886, 2020). "Several STAT proteins have been found to be linked to the cancer pathology, for example, constitutively activated STAT1, STAT3 and STAT5 have been found in breast, lung, prostate and pancreatic cancers, and other haematological malignancies." (PMID 32872372, 2020). "Oligo-Fucoidan can attenuate the negative effects of etoposide (ETO) chemotherapy that promotes IL-6 and MCP-1/CCL2 production in aggressive HCT116 cancer cells which activate Stat3 and Stat6 signaling, respectively." (PMID 32059469, 2020). "Many studies indicate that STAT3 participates in regulating critical processes for the development and progression of cancer." (PMID 33158194, 2020). "Additional research showed curcumin’s potential to reduce STAT3 phosphorylation in small-cell lung cancer cells by desensitizing the downstream target genes, which was accountable for cancer cell proliferation." (PMID 32545187, 2020).
cancer (continued). "All these data confirm the crucial role of STAT3-dependent signaling on the biology of cancer-reprogrammed myeloid cells." (PMID 33584695, 2020). "MSDCs produce ROS in many cancer types through increased expression of NOX2 which is regulated by STAT3." (PMID 33143283, 2020). "IL-6-mediated activation of JAK/STAT3 signaling has been shown to increase the proliferation of cancer cells 28,29." (PMID 33123268, 2020). "EGF/EGFR signal transduction has been known to lead to the constitutive activation of downstream signaling pathways associated with MAPKs, STAT3, and PI3K for regulating PD-L1 expression in various cancer cells." (PMID 32204508, 2020). "Many STAT3 target genes related to cancer are also regulated at the translational level by cap‐dependent translation." (PMID 32495998, 2020). "JW-55 was the selective Wnt/β-catenin signaling pathway inhibitor, and STAT3 was also approved to regulate Wnt/β-catenin signaling in the development of cancer." (PMID 32486001, 2020). "Some reports describe higher levels of phospho-STAT3 and lower levels of ROS than those in radiosensitive cancer cells." (PMID 32872659, 2020). "Recently, the activation of a signal transducer and activator of transcription 3 (STAT3) has been described as an alternative resistance mechanism allowing cancer cells to escape the EGFR signaling or the TKI suppression." (PMID 32438613, 2020). "Both NF-κB and STAT3 are important cancer-related inflammatory regulators, and they can interact with each other to enhance the activation of the inflammatory pathway and regulate the expression of the set of target genes." (PMID 31511651, 2020). "Remarkably, STAT3 was closely correlated with the response to specified inhibitors and natural compounds in cancer." (PMID 32486001, 2020). "Growing evidence has indicated that several cancer-associated signaling pathways are involved in the regulation of EMT, including the JAK/STAT3 pathway." (PMID 33024090, 2020). "Previous reports have reported that STAT3 signaling is a regulator of PD-L1 expression in mouse models and cancer cell lines." (PMID 32727138, 2020). "STAT3 is an important transcriptional factor that has been identified to regulate cancer initiation and progression." (PMID 32174012, 2020). "We observed a clear pattern of downregulation of p65 NFκB and upregulation of STAT3 total protein expression and phosphorylation among the high-grade cancer patients compared to healthy donors." (PMID 33330068, 2020). "STAT3 also mediates the expression of proteins involved in other hallmarks of cancer, such as invasion/metastasis and angiogenesis." (PMID 33053804, 2020). "On the basis of these observations, we assessed the importance of STAT3 signaling with regards to the ability of AT-I to mediate anti-cancer effects in CRC cells." (PMID 32273843, 2020). "In this review, we focus on the post-translational modifications of STAT3 by oxidative stress and how the modification of STAT3 regulates cell metabolism, particularly in the metabolic pathways in cancer cells." (PMID 33003453, 2020). "Chronic inflammation, by activating two major signaling pathways, NFκB and STAT3, contributes critically to cancer initiation, progression, and metastasis." (PMID 31860165, 2020). "STAT3 is activated in several cancers and is proved to be involved in cancer cell proliferation, migration, and invasion." (PMID 33680016, 2020). "Multiple signaling pathways converge at STAT3, making it a master regulator mediating molecular events that result in cancer progression." (PMID 33206698, 2020). "Few reports have investigated the effect of STAT3 acetylation on metabolism; however, this effect appears to be an important mechanism in cancer metabolism." (PMID 33003453, 2020).